AR (androgen receptor)
Diseases named in the same sentence as AR in open-access papers (continued):
Sharing a sentence is not in itself a finding about the gene and the disease.
tumor (continued). "Similarly, GCDFP-15 was not a significant prognostic marker for OS or DFS within the biological tumor types (HR+/HER-, HR+/HER2+, HR-/HER2+, HR-/HER2-) or in Farmer tumor types (HR + (AR+/-), HR-/AR+, HR-/AR-; p < 0.05 for each test, not shown)." (PMID 25070172, 2014). "No apparent changes in the levels of AR translocated to the nucleus were observed after NWD1 over-expression This direct correlation between NWD1 and AR protein levels is consistent with our observations in PCa tumor samples." (PMID 24681825, 2014). "Rather, the presence or absence of progesterone receptor (PR), ER, and AR in HCC and their titers did not have any correlation with alcohol abuse, serum alpha-fetoprotein (AFP) levels, hepatitis B virus markers, or histopathologic types of the tumor." (PMID 23484104, 2013). "Tumor cells were negative for CK20, AR, ER, PR, EGFR, and Her-2/neu oncoprotein." (PMID 23419146, 2013). "Tumor cells were negative for CEA, AR, ER, PR, EGFR, and Her-2/neu oncoprotein." (PMID 23419146, 2013). "Strikingly, the HPCa70 xenograft tumor, which was established by implanting tumor pieces without Hs5 cells presented a fully undifferentiated morphology and IHC staining was negative for PSA and weakly positive for AR." (PMID 23451107, 2013). "In addition, tumor cells in CRPC may exhibit increased extragonadal androgen production and AR activation independent of ligands." (PMID 38674385, 2024). "Since SSTR1 is downregulated after ARSI, we examined the reciprocal relationship between the AR/FOXA1/HOXB13 transcription machinery and SSTR1 expression, specifically the effect of testosterone (as opposed to ADT and ARSIs) on SSTR1 expression and tumor growth." (PMID 39352383, 2024). "Although our short-term ex vivo explant experiment revealed that CU-PC01 tumours are not initially sensitive to AKT inhibition, future work to explore the long-term efficacy of PI3K/AKT-directed therapy in vivo is warranted to inform AR-negative mCRPC treatment decisions in the clinic." (PMID 38667288, 2024). "Although AR was already cytoplasmic 1 day after castration and the weight of the seminal vesicles was reduced after 3 days in both mouse lines (Fig EV2A–C), histological analyses revealed tumor regression in prostates of Pten/Hif1a(i)pe−/− mice but not in those of Pten(i)pe−/− ones." (PMID 37070472, 2023). "Finally, the tumor cells did not express CD117, S100, androgen receptor or DOG-1 (data not shown)." (PMID 37847488, 2023). "However, in AR negative CRPC cells, KIF15 may promote tumor cell proliferation through activating EGFR signaling pathway." (PMID 34804913, 2021). "Preclinical studies have shown that enzalutamide promotes tumor cell apoptosis in LAR and non-LAR TNBC subtype cell lines, thus suggesting that enzalutamide may be available even in TNBC cell lines with weakly positive AR expression." (PMID 32587770, 2020). "To investigate the potential anti-tumor activity of the new synthesized molecules, we tested their effect on the proliferation of cancer cell lines, in particular PC3 and DU145, two of the most representative in vitro models of PCa, in which AR is not expressed." (PMID 30577600, 2018).
tumor (continued). "Although WCE induced cell apoptosis in AR-positive LNCaP and 22Rv1 cells more significantly than in AR-negative PC-3 and DU145 cells, unexpectedly, the results showed that WCE also significantly inhibited the tumor growth without affecting the body weight in both the mouse models." (PMID 29142311, 2017). "In addition, it has been indicated that prostate CSCs do not express androgen receptors (AR) and may not respond to ADT as mature tumor cells do." (PMID 25380390, 2014). "In addition, it is now accepted that PSA gene expression is due to AR transcriptional activity, and therefore altered AR transcription could lead to declines in PSA levels, but not in the desired reduction in tumor growth." (PMID 22738151, 2012). "Hence, this study investigated the protein expression of ERα, ERβ, PGR, and AR in paired non-cancerous and cancerous tissues collected from patients diagnosed with CRC, and the results were analyzed according to gender, age, clinical stage, and tumor anatomical sites." (PMID 37206439, 2023). "To dissect the molecular mechanisms how hypoxia-suppressed AR can alter the RCC CSCs phenotype, we focused on the long noncoding RNAs (lncRNAs) as recent studies indicated that they might play important roles to promote tumor progression in a variety of settings." (PMID 36397101, 2022). "Moreover, the combinatory treatment of LNCaP xenograft model of CRPC significantly reduced tumor size without relapse compared to monotherapy with either Enz or AZD5363, indicating that a combinatory treatment by inhibition of both the AKT and AR pathways could be beneficial." (PMID 33810413, 2021).
cancer (2,140 papers, 2001 to 2026). A tumor composed of atypical neoplastic, often pleomorphic cells that invade other tissues. "Other KLKs have emerged as key players in PCa pathogenesis, particularly KLK2, KLK4, and KLK14, which are implicated in cancer progression through protease activity, AR modulation, and interaction with extracellular matrix components." (PMID 41531507, 2026). "The upstream regulatory role of the androgen receptor on the NF-κB2/p52 pathway in cancer-associated fibroblasts was elucidated and validated using CRISPR-Cas9, ChIP-qPCR, and dual-luciferase reporter assays." (PMID 42244988, 2026). "Extending these observations, we found that AR activity is negatively associated with IFNγ pathway activity at the pan-cancer level." (PMID 41486951, 2026). "In females, the AR/ERα ratio showed significant associations with PFI in a few cancers although most HRs were close to 1 or derived from small sample sizes." (PMID 41486951, 2026). "In conclusion, AR-mutated mCRPC frequently exhibits low AR-V7 expression, arguably explaining the enhanced sensitivity to ARPIs observed in these cancers." (PMID 41919503, 2026). "AR signaling supports growth and reproductive function, but excessive or prolonged AR activity has been linked to pro-aging effects, particularly through increased oxidative stress, inflammation, and cancer risk, especially in androgen-sensitive tissues." (PMID 40275190, 2025). "While APP overexpression and androgen receptor (AR) signaling are each associated with cancer progression, the connection between androgens and APP processing in cancer has not been thoroughly investigated." (PMID 41614805, 2025). "In PCa, the degree of DNA methylation correlates with the expression of cancer-associated genes (such as androgen receptor signaling) and identifies cancer stages." (PMID 40723280, 2025). "Based upon our GSEA data suggesting a role for AR in regulating E2F targets—transcription factors regulating the cell cycle and implicated in cancer progression, invasion, and metastasis—we examined the invasive potential of our AR KO clones." (PMID 40805231, 2025). "The androgen receptor, AR, almost certainly contributes to sex biases; androgens have been implicated in sex bias in a number of cancers through interactions with the CD8 + T cell exhaustion program." (PMID 41024254, 2025). "In ESCC and EAC, lower circulating T levels have been associated with increased cancer risk, whereas higher AR expression is observed in more advanced tumors and correlates with poorer survival." (PMID 41228208, 2025). "ARLNC1 (androgen receptor‐regulated long noncoding RNA 1) has been shown to exhibit a highly specific expression pattern in tissues of PCA and is strongly associated with AR signalling in cancer progression." (PMID 40259205, 2025). "Overall, these studies highlight that both the ER and AR regulate a wide range of immune cell functions, explaining the sexual dimorphism in inflammation, cancer response, and disease susceptibility." (PMID 40406098, 2025). "22Rv1 is mutated in AR, C4-2 is derived from androgen-dependent human LNCaP and PC-3 is an androgen-independent cancer cell type." (PMID 40374533, 2025). "In this review, we explored the interconnected biological systems underlying PCa progression, focusing on how AR signaling, the circadian clock, and cellular senescence converge to influence cellular senescence in cancer cells." (PMID 41264145, 2025). "Pharmacological inhibition of AR improves therapeutic response, emphasizing the critical role of sex hormones in cancer risk and treatment outcome." (PMID 40361239, 2025). "Together, these germline risk variants would dysregulate the FOXA1/AR equilibrium via remodeling promoter accessibility, potentially converting LE-2 cells into a cancer-prone state." (PMID 41468516, 2025).
cancer (continued). "In CRPC, cancer cells adapt to survive at low androgen levels through mechanisms such as AR overexpression, AR point mutations, alterations in androgen biosynthesis, and changes in androgen cofactors." (PMID 41465509, 2025). "Biological function validation is critical, involving testing the efficacy of candidate drugs in cell lines with specific AR mutations to assess their impact on AR activity inhibition and cancer cell proliferation." (PMID 40008000, 2025). "Within pT2–pT4 carcinomas, high AR immunostaining was associated with GATA3 (p < 0.0001) and CK20 (p < 0.0001) positivity, p63 expression loss (p = 0.0013), and low PD-L1 expression in cancer cells (p < 0.0001)." (PMID 41463239, 2025). "In the cohort with pT2–pT4 carcinomas that were treated by radical cystectomy, AR positivity was significantly associated with an unfavorable overall survival (OS) in univariate analysis (p = 0.0210; HR = 1.48, 95% CI 1.06–2.05)." (PMID 41463239, 2025). "This immunotherapy is a DNA vaccine encoding the LBD of AR that consequently induces a CD8+T cell-mediated immune response against cancer cells overexpressing AR." (PMID 38201308, 2024). "By contrast, a smaller subset of CRPC tumors lose dependence on the AR signaling axis and acquire aggressive variant states characterized by high cancer cell plasticity, which can manifest in neuroendocrine prostate cancer (NEPC)." (PMID 39117800, 2024). "For clinically locally advanced cancer, SRC-1 (p < 0.005), SRC-2 (p < 0.0005), SRC-3 (p < 0.05), AR (p < 0.05), and AR-V7 (p < 0.0005) super-expression were significantly associated with locally advanced cancer." (PMID 38305916, 2024). "Drugs such as onalespib have been tested for their ability to inhibit HSP90, preventing AR splice variant expression and slowing cancer progression." (PMID 39512805, 2024). "CK1α is one isoform predicted to regulate AR activity via phosphorylation and has been implicated in the progression of several other cancer types." (PMID 39001502, 2024). "Many of these phenotypes from the top network are directly related to the activity of ESR2 and AR, such as reproductive system-associated cancers." (PMID 39598420, 2024). "Because of this cancer's strong association with AR signalling, androgen deprivation therapies (ADTs) were developed to help curb the growth and development of the disease." (PMID 39410867, 2024). "This year’s symposium focused on the involvement of the AR in PCa, the second leading cause of cancer-related deaths in men." (PMID 38238739, 2024). "The androgen receptor (AR), expressed in both prostate stromal and epithelial cells, has particularly been implicated in cell cancer adhesion and invasion." (PMID 39459070, 2024). "It arises due to various mechanisms, including AR signaling pathway alterations, such as AR amplification or mutations, allowing cancer cells to survive and proliferate." (PMID 38920635, 2024). "A multicenter retrospective analysis of M0/M1 CRPC patients with pre- or post-docetaxel androgen receptor axis-targeted treatment showed that NLR ≥ 2.5 is an independent risk factor for poorer cancer-specific survival (CSS) and rPFS." (PMID 39335736, 2024). "Phenotypic plasticity is a hallmark of cancer and is increasingly realized as a mechanism of resistance to androgen receptor–targeted (AR-targeted) therapy." (PMID 39560993, 2024). "Immortalized smooth muscle and fibroblast cell lines (PM151T, PF179T-NAF, PF179T-CAF), as well as primary isolated normal and cancer-associated fibroblasts (NAFs, CAFs), showed strong GR and weak AR expression patterns." (PMID 38017134, 2024). "Here, we show that cancer-associated fibroblasts (CAFs) increased epithelial 3βHSD1 expression, induced androgen synthesis, activated the androgen receptor, and induced CRPC." (PMID 37009898, 2023).
cancer (continued). "Overall, the cellular positivity ranged from 3% to 95% with combined 2+ & 3+ intensities in 35% (11/31), 32% (10/31), and 65% (20/31) of ER, PR, and AR respectively, indicative of higher rate and stronger expression of AR in this diagnostic cancer category." (PMID 37725629, 2023). "It is known that the therapy-resistant cancer cells remain highly dependent on sustained AR signaling resulting from mechanisms such as AR amplification, mutations, splice variants expression, or activation by alternative co-activators." (PMID 36893587, 2023). "In PCA, YAP1 only exist in basal/dedifferentiated PCA and stroma cells with little androgen receptor (AR) signaling activation, which contribute to the development of anti-androgen resistance caused by induction of cancer stemness." (PMID 36973255, 2023). "Loss of Rb during cancer progression leads to an unsupervised activation of E2F, thereby increasing the protein levels of AR." (PMID 37363926, 2023). "One target can carry different disease profiles; for example, AR has been associated with both cancer and digestive system disorders." (PMID 37701374, 2023). "This androgen receptor-lipid axis was associated with cancer progression and drug response and is considered as a therapeutic vulnerability." (PMID 36347965, 2023). "CPRC has been linked to the formation of at least 20 different types of miRNAs, which take part in a variety of pathogenic pathways, such as AR-related cell proliferation, cancer cell survival, apoptosis, or EMT." (PMID 36902032, 2023). "Other mechanisms of AR’s role in cancer risks have been proposed to provide a potential protective effect, specifically cancer-associated fibroblast (CAF) activation." (PMID 36833272, 2023). "cAMP and its effector PKA act to coordinate signalling cascades which are implicated in cancer cell growth and involved in cross-talk with AR signalling." (PMID 37830741, 2023). "This process is not fully understood; however, continuous AR signaling, AR gene amplification, mutations, ligand-independent activation, coregulators, and cancer stem cell (CSC) recruitment are thought to be involved." (PMID 37190236, 2023). "Current evidence, although limited, indicates that AR activation in CSCs from different cancers can regulate the expression of factors associated with stemness and their self-renewal capacity." (PMID 37894767, 2023). "Steroid hormone receptors (SHRs), such as androgen receptor (AR), estrogen receptor (ER), and progesterone receptor (PR), are transcription factors associated with the development and involvement of many cancers." (PMID 36230806, 2022). "In this review, we summarized efforts in determining the risk of length variations in the polymorphic regions of AR to certain types of cancer." (PMID 36388907, 2022). "Some glycosylation enzymes (GALNT7, GCNT1, TAP1, PGM3, etc.)are under the control of AR and link to the synthesis of cancer-associated glycans such as sialyl-Tn (sTn), sialyl LewisX (SleX)." (PMID 35853851, 2022). "Unsurprisingly, aberrant expression ER and AR are risk factors in many cancers, including prostate, breast and lung cancers." (PMID 35812730, 2022). "We have demonstrated that in the presence of enzalutamide or darolutamide, AR is enriched in the distal elements of cancer-related genes such as NR3C1 (encoding GR) and SLC7A11, and upregulates their expression in both ADPC and CPRC cell models." (PMID 35864113, 2022). "The expression of the CAF-related marker genes SDF1, FAP, αSMA, and AR for activated phenotype of cancer associated fibroblasts were inconsistently deregulated in the six analyzed paired samples." (PMID 35740605, 2022). "In PTEN deficient cancer cells, there exists a reciprocal activation between the AR and PI3K/Akt signalling." (PMID 35832549, 2022). "Despite the differential rates of AR expression, notably, the risk factors for malignant tumors are indispensable and deserve greater research attention." (PMID 35517428, 2022).